ACE (angiotensin I converting enzyme)
Diseases named in the same sentence as ACE in open-access papers (continued):
Sharing a sentence is not in itself a finding about the gene and the disease.
Hypertension (continued). "The RAAS is a key player in maintaining blood pressure and volume balance, and its inhibition with ACE inhibitors (ACE-Is) has proven to be an effective treatment strategy in conditions such as hypertension and congestive heart failure." (PMID 38256315, 2023). "We evaluated the inhibitory effect of phytochemicals derived from beetroot against ACE and AR in hypertension." (PMID 37822725, 2023). "His most important contributions include pre-clinical and clinical studies that introduced inhibition of angiotensin receptor and angiotensin-converting enzyme (ACE) as effective therapies for the treatment of patients with hypertension or heart failure." (PMID 37600045, 2023). "The BMI, hypertension, smoking, follow-up time, and use of acetylsalicylic acid, ACE inhibitors, and ARB data were all studied." (PMID 37959300, 2023). "There is robust evidence on the benefits of beta-blocker and ACE inhibitor use in patients with hypertension and elevated heart rate, CAD, AF, and heart failure." (PMID 34533690, 2023). "We included the variables with a P value ≤ 0.05 such as eNOS Glu298Asp, ACE I/D, and AGT M235T polymorphisms and traditional risk factors, and we used hypertension as the dependent variable." (PMID 36845669, 2023). "A high concentration of ACE leads to increased synthesis of angiotensin II and the inactivation of bradykinin, which results in increased vascular resistance and hypertension." (PMID 37206099, 2023). "Quinapril is an angiotensin-converting enzyme (ACE) inhibitor used to treat hypertension and congestive heart failure." (PMID 37375294, 2023). "In 2020, there were 123 million defined daily doses (DDDs) of alpha blockers used to treat hypertension compared with 2,589 million DDDs of calcium channel blockers and 6,050 million DDDs of ACE inhibitors (Schwabe/Ludwig Hrsg, 2021)." (PMID 37876727, 2023). "Inhibitors of DPP-IV and/or ACE are regularly applied in therapy to lower morbidity and mortality of patients with type II diabetes and/or hypertension." (PMID 37284652, 2023). "The patient, affected by severe hypertension and gallbladder calculosis, was on therapy with an ACE-inhibitor and ursodeoxycholic acid." (PMID 37894265, 2023). "Tachycardia and hypertension can be treated with beta-blockers, calcium antagonists, or angiotensin-converting enzyme (ACE) inhibitors." (PMID 37065381, 2023). "Individuals with hypertension were more likely to use diuretic drugs than angiotensin-converting enzyme (ACE) inhibitors (10.9 vs. 2.3%), whereas 7.5 % take ACE inhibitors or diuretic drugs." (PMID 37397782, 2023). "We aimed to investigate the relationship between angiotensin converting enzyme (ACE) levels, ACE gene polymorphism, type 2 diabetes (T2DM), and hypertension (HT) and the prognosis of COVID-19 infection." (PMID 37432962, 2023). "One of the main drugs prescribed for hypertension since the early 1980s is the small molecule ACE inhibitor captopril." (PMID 37372091, 2023). "Multiple studies have shown that treatment for hypertension (e.g., ACE inhibitors) and hyperlipidemia, as well as DMARD treatment with methotrexate, can modulate sRAGE levels." (PMID 36769213, 2023). "ACE inhibitors such as ramipril and lisinopril are used to treat hypertension by inhibiting the production of angiotensin II, a protein involved in the constriction of blood vessels." (PMID 38235056, 2023). "Subsequent studies showed promise with omapatrilat, a vasopeptidase inhibitor with combined neprilysin and ACE inhibition in patients with HF and hypertension." (PMID 36777165, 2023). "The discovery of captopril,the first ACE inhibitor, has pavedthe way for the development of numerous ACE inhibitors used in thetreatment of conditions such as hypertension, chronic heart failure,and kidney diseases." (PMID 38027387, 2023). "Ramipril is an Angiotensin-converting enzyme (ACE) inhibitors and is used to treat hypertension, heart failure, and after myocardial infarction." (PMID 36922850, 2023).
Hypertension (continued). "Arterial Hypertension (AHT) is treated using drugs that inhibit the Angiotensin I-Converting Enzyme (ACE-1; EC 3.4.15.1) such as Enalapril® or Captopril©." (PMID 36827131, 2023). "Angiotensin-converting enzyme (ACE) inhibitors (ACEIs) are first-line cornerstone drugs that are widely used to treat hypertension and heart failure." (PMID 37799968, 2023). "The angiotensin-converting enzyme (ACE) gene, which encodes an enzyme that converts angiotensin I to angiotensin II, has been linked to hypertension and cardiovascular disease." (PMID 37416924, 2023). "PRD is used in heart failure and hypertension as it is an inhibitor of the angiotensin-converting enzyme (ACE)." (PMID 37349827, 2023). "Currently, several drugs used for hypertension, including angiotensin-converting enzyme (ACE) inhibitors and angiotensin II receptor blockers (ARBs)." (PMID 37340199, 2023). "Our results suggest that evaluating genetic variation in ACE and ACE2 genes can be a useful new diagnostic approach for clinical assessment and risk management of COVID-19 with hypertension." (PMID 37667339, 2023). "For patients with hypertension (n = 70, 36.5%), 38 (54.3%) were under therapy with angiotensin-converting enzyme (ACE) inhibitors or angiotensin II receptor blockers (ARBs)." (PMID 37238660, 2023). "ACE inhibitors and beta-blockers represent two of the five main drug classes recommended for the treatment of arterial hypertension." (PMID 34533690, 2023). "Levels of cortisol and angiotensin-converting enzyme (ACE) (an indicator of hypertension) were measured from plasma." (PMID 37333097, 2023). "Controlling blood pressure control by inhibiting ACE activity is regarded as a preventive and therapeutic strategy for hypertension." (PMID 37446242, 2023). "Due to these multiple activities, ACE inhibitors always constitute the first line of treatment for controlling hypertension." (PMID 37360301, 2023). "In a study 48 of high fructose-induced hypertension in Dahl-SS rats, an ACE inhibitor attenuated hypertension and renal damage after 12 weeks of treatment." (PMID 37082725, 2023). "The Renin-Angiotensin-Aldosterone System (RAAS) is a primary target for hypertension treatment, and it is primarily treated through drugs that inhibit the Angiotensin I-Converting Enzyme (ACE)." (PMID 38002167, 2023). "Biologically active peptides released from food proteins are widely used to treat hypertension, and their action pathways include but are not limited to ACE inhibition." (PMID 37297335, 2023). "Hypertension and a history of preeclampsia/eclampsia were more frequent among those with the ACE DD genotype than among those with the ID and II genotypes; 44.4% vs. 8.0%, p = 0.031 and 77.8% vs. 32.0%, p = 0.025, respectively." (PMID 37089887, 2023). "In the context of Hypertension, many legumes, such as the common bean, have been found to contain bioactive peptides that exhibit inhibitory effects against angiotensin-converting enzyme (ACE) activity." (PMID 37960212, 2023). "Genetic polymorphisms in ACE and ACE2 genes have been shown to confer susceptibility to hypertension." (PMID 37667339, 2023). "The choice of an antihypertensive drug is based on individual tolerability and efficacy, however, angiotensin-converting enzyme (ACE) and angiotensin II receptor blockers are considered first-line medication for hypertension." (PMID 37822725, 2023). "Current first-line treatments for hypertension include diuretics, angiotensin-converting enzyme (ACE) inhibitors, and/or angiotensin receptor blockers (ARBs)." (PMID 36266539, 2023). "Plant protein hydrolysates have shown strong inhibitory activities against α‐glucosidase, α‐amylase, and ACE toward the prevention and management of diabetes and hypertension." (PMID 36911847, 2023). "Nevertheless, hypertension rates in Africa cannot be solely attributed to ACE SNPs, since hypertension is a multifactorial disease with a strong environmental component, including diet and physical activity." (PMID 37964928, 2023).
Hypertension (continued). "Another study of pregnant women with hypertension in India reported significantly higher ACE levels in the DD genotype group than in the ID and DD genotype groups." (PMID 37089887, 2023). "Undecapeptide is the central peptide molecule in the peptide base material of Stropharia rugosoannulata, and angiotensin-converting enzyme (ACE) plays a crucial role in hypertension." (PMID 37761171, 2023). "ACE inhibition is the most recent advancement in the treatment of hypertension, and in the last recent years, it has become increasingly admired as the primary variety in the pharmacotherapy of this disease." (PMID 37389408, 2023). "Based on this physiological role, ACE inhibitors often regulate ACE activity in conditions such as hypertension and cardiovascular diseases, including atherosclerosis." (PMID 37928535, 2023). "In an open trial of the combination of an ACE inhibitor and a calcium channel blocker in patients with hypertension, an improvement in PWV was seen after 12 months." (PMID 36408896, 2023). "The angiotensin‐converting enzyme (ACE) inhibition by phenolic compounds has been used to treat hypertension." (PMID 37324906, 2023). "ACE inhibitors help to reduce the occurrence of hypertension, there is still confusion that which option is best either to inhibit the receptors that bind angiotensin II and signal vasoconstriction or ACE directly." (PMID 37854353, 2023). "Angiotensin-converting enzyme (ACE) has a significant role in the regulation of blood pressure and ACE inhibition with inhibitory peptides is considered a major target to prevent hypertension." (PMID 36770716, 2023). "First, it embeds the racialized disparity in hypertension burden and a supposed racialized differential response to ACE inhibitors in an appealing and intuitive evolutionary narrative." (PMID 38076215, 2023). "Several polyphenols have the ability to inhibit angiotensin-converting enzyme (ACE), an enzyme linked to the development of hypertension." (PMID 37959005, 2023). "Apart from rhinitis (n = 68, 7.5%), obesity (n = 60, 6.6%), and hypertension (n = 98, 10.8%, all in patients taking angiotensin-converting enzyme [ACE] inhibitors), the VBDs were healthy." (PMID 37253276, 2023). "In the AHA/ACC 2017 hypertension guidelines, an ACE inhibitor is the preferred drug if albuminuria is present, although an ARB can be used in case of ACE inhibitor intolerance." (PMID 34533690, 2023). "Angiotensin receptor blockers (ARB), angiotensin converting enzyme (ACE) inhibitors, calcium channel blockers and diuretics have been the most widely used treatments for hypertension." (PMID 37520120, 2023). "Men with hypertension comorbidity, GG (ACE), and TT (ACE2) genotypes tended to have moderate-to-severe symptoms (25%)." (PMID 37667339, 2023). "L-NAME activates ACE and increases ANG II production by causing vascular inflammation and atherosclerosis, contributing to hypertension." (PMID 37214130, 2023). "Although a few patients were taking ACE inhibitors because of hypertension, clinical trials on ACE inhibitors to prevent cardiac events would be desirable in the future." (PMID 37308130, 2023). "Due to these adverse effects, many scientists have explored bioactive compounds from natural sources that possess ACE inhibitory properties for the potential treatment of hypertension." (PMID 37174355, 2023). "During the onset of hypertension, angiotensin is hydrolyzed to angiotensin I, which is then converted to angiotensin II by the angiotensin converting enzyme (ACE)." (PMID 37576957, 2023). "In contrast, ACE inhibition blocks the first step in the renin-angiotensin system (reduction of angiotensin II), resulting in the treatment of hypertension and enhancing the antioxidative defense system." (PMID 36985395, 2023). "Inhibiting its activity can induce angioedema outbreak through insufficient bradykinin degradation (Anderson and deShazo, 1990) as observed in hypertension patients medicated with ACE inhibitors (ACEi-AE)." (PMID 37470035, 2023).
Hypertension (continued). "Angiotensin II receptor blockers (ARBs) and Angiotensin-converting enzyme (ACE) inhibitors are the gold standard treatment for hypertension." (PMID 37854465, 2023). "The blood-pressure-lowering effects of ACE-inhibitory peptides have been demonstrated in several studies with subjects suffering from hypertension." (PMID 38004148, 2023). "Several studies have shown that comorbid hypertension can worsen the prognosis of COVID-19 because the consumption of ACE inhibitors and ARBs as hypertension drug interventions can actually worsen COVID-19." (PMID 37425387, 2023). "There are some risk factors related to the appearance of ARs during immunotherapy, which are the following: hypertension, mastocytosis, β-blockers/ACE inhibitors intake, serum basal tryptase concentration, male sex, old age, etc.." (PMID 37243083, 2023). "In early studies, the combination of neprilysin inhibitors with ACE inhibitors showed increased synergistic efficacy for BP lowering in patients with hypertension." (PMID 36777165, 2023). "Inhibition of angiotensin-I converting enzyme (ACE) is an important means of treating hypertension since it plays an important regulatory function in the renin-angiotensin system." (PMID 37761189, 2023). "On the other hand, patients with hypertension should theoretically have increased expression of ACE and decreased expression of ACE2, the latter being a protective enzyme against elevated blood pressure levels." (PMID 37762779, 2023). "Commonly prescribed medications for hypertension include ACE inhibitors, ARBs, beta-blockers, diuretics, calcium channel blockers, and alpha-blockers." (PMID 37868469, 2023). "In controlling hypertension, inhibition of ACE results in lower levels of the active vasoconstrictor, angiotensin II, leading to lower blood pressure." (PMID 38231711, 2023). "For patients with hypertension (47.47 percent), the beta-blocker (43 percent) was the most often recommended medicine alone, followed by ACE inhibitors (28 percent), ARBs (16 percent), CCBs (9 percent), and diuretics (4 percent)." (PMID 37444807, 2023). "Diabetes and hypertension are treated with ACE inhibitors and angiotensin II type-I receptor blockers (ARBs), which causes an increase in ACE2 expression and infection with COVID-19146,147." (PMID 36747045, 2023). "The ACE inhibition peptide is usually used for hypertension control to prevent the conversion of angiotensin I to angiotensin II." (PMID 37893466, 2023). "To date, the key role of the ACE–Ang II–AT1R axis in hypertension has been well evidenced, and Angiotensin-I-Converting Enzyme (ACE) is one of the main targets of antihypertensive drugs." (PMID 37297512, 2023). "In experimental models, VEGF-TKIs correlate with a decrease in renin activity, but angiotensin-converting enzyme (ACE) inhibitors have a limited impact on hypertension compared with Ca2+-channel blockers." (PMID 36836722, 2023). "Angiotensin-converting enzyme (ACE) inhibitors manage hypertension and improve endothelial function by reducing vascular resistance." (PMID 37790001, 2023). "Previous studies have found potential interactions between ACE, AGT, angiotensin II type 1 receptor (AGTR1), and α adducin (ADD1) variants and correlations between them and clinical endpoints in individuals with hypertension." (PMID 37091860, 2023). "ACE inhibitors are widely used clinically for the treatment of hypertension, however, compared with non–ACE inhibitor antihypertensive medications, ACE inhibitors can reduce IQ in male hypertensive patients." (PMID 36875692, 2023). "Secondly, licochalcone A not only directly inhibited the activation of the TNF-α/NF-κB pathway but also exhibited strong potential in the inhibition of angiotensin converting enzyme (ACE) in hypertension, heart failures and myocardial infarction." (PMID 36713834, 2023). "Inhibition of ACE is a modern therapeutic target in the treatment of hypertension and related CVDs8,9." (PMID 36639377, 2023).
Hypertension (continued). "Obesity is associated with the activation of the ACE/Ang II/AT1R axis, with the overactivation of Ang II in obesity stimulating AT1R to promote hypertension, insulin resistance, and energy imbalance." (PMID 36843595, 2023). "ACE inhibitors are important in the treatment of hypertension, which can effectively block the transformation of Ang I into Ang II, thus achieving the effect of treating hypertension." (PMID 36766030, 2023). "The use of the angiotensin-converting enzyme (ACE) inhibitor to regulate blood pressure and cardiovascular function as a means to control hypertension and prevent CVD is currently considered to be very promising." (PMID 37297391, 2023). "The primary pharmacological agents utilized in the management of hypertension include diuretics, angiotensin-converting enzyme (ACE) inhibitors or angiotensin receptor blockers (ARBs), beta-blockers, and calcium channel blockers (CCBs)." (PMID 37614749, 2023). "These have suggested that ACE inhibitors and ARBs reduce the incidence of new-onset AF in a variety of conditions, including hypertension, left ventricular dysfunction, and after coronary artery bypass graft surgery." (PMID 34533690, 2023). "Hypertension is easy to diagnose and treat with first-line antihypertensive drugs, such as ACE inhibitors, ARBs, or BAAs." (PMID 36768635, 2023). "For instance, they can inhibit the angiotensin-converting enzyme (ACE) in hypertension, acetylcholinesterase in Alzheimer’s disease, the carbohydrate hydrolyzing enzyme in type 2 diabetes mellitus, and tyrosinase in skin hyperpigmentation." (PMID 36904035, 2023). "Initial uncertainty about the role of hypertension and its treatment led to heterogeneous management and major changes in antihypertensive treatment, mainly at the cost of discontinuation of ACE inhibitors or ARAIIs." (PMID 37512012, 2023). "Although regular treatment with ACE inhibitors appears to be a factor associated with the development of HF, in this case, it may be acting as a confounding factor because it is a common treatment for patients with previous HF, nephropathy, or hypertension, which are risk factors for HF." (PMID 37510764, 2023). "Several chemical synthetic ACE inhibitors, such as captopril, enalaprilat, temocapril and lisinopril, have been used in hypertension treatment, but most of them produce side effects." (PMID 37049880, 2023). "Certainly, ACE-inhibitory peptides produced from legume proteins have gained a lot of interest recently, and their ability to prevent hypertension in vitro and in vivo has been thoroughly investigated." (PMID 36985395, 2023). "Spirapril, a spirocyclic inhibitor of the angiotensin-converting enzyme (ACE) had been originated and developed by the Schering-Plough Corporation (now Merck & Co.)and was approved in 1995 for the treatment of hypertension." (PMID 37241950, 2023). "These include angiotensin-converting enzyme (ACE) inhibitors for treating hypertension, HIV-1 protease inhibitors for treating AIDS, thrombin inhibitors for treating stroke, and an elastase inhibitor for treating systemic inflammatory response syndrome (SIRS)." (PMID 37368657, 2023). "In the 2018 ESC/ESH guidelines for the management of arterial hypertension, initial dual treatment combinations comprise an ACE inhibitor or angiotensin receptor blocker (ARB) with either a calcium channel blocker (CCB) or thiazide/thiazide-like diuretic." (PMID 34533690, 2023). "Currently, food-derived ACE-inhibitory compounds are being sought to treat hypertension, as it is one of the most serious health problems worldwide." (PMID 37241977, 2023). "The possible mechanisms of ACE inhibitory activity were also investigated, and preliminary studies were conducted to investigate the effect of peptides on hypertension-related NO expression at the cellular level." (PMID 37242257, 2023).